MDM4 (MDM4 regulator of p53)
Diseases named in the same sentence as MDM4 in open-access papers (continued):
Sharing a sentence is not in itself a finding about the gene and the disease.
tumor (continued). "Importantly, MDM4 expression was markedly decreased upon miR-1307-5p overexpression and negatively correlated with miR-1307-5p expression in the mouse tumor tissues." (PMID 35778656, 2022). "For in vitro studies, the role of IKBKE, IGF1R, NOTCH3 and MDM4 in tumorigenesis and tumour metastasis have been reported and have provided clinicians with potential insights for understanding the biological behaviour of TNBC and exploring treatment strategies for heavily treated patients." (PMID 34396843, 2021). "The whole exome sequencing found MDM4 amplified in tumor cells." (PMID 34054730, 2021). "Indeed, the OS probability is doubled in patients that express high levels of MDM4 starting from 6 years after tumor appearance." (PMID 34052831, 2021). "As an example, we found an objective response in a patient with an MDM4 alteration, which has been associated with hyper-progression in other tumor types or a possible lack of correlation between TMB and therapy response." (PMID 33353145, 2020). "In Mdm4Tg10 mice, the lower levels of Mdm4 were unable to accelerate tumor formation, supporting the hypothesis that Mdm4 tumorigenic activity is dependent on the amount of Mdm4, in agreement with a previous report." (PMID 31547268, 2019). "Interestingly, ICI treatment reduced tumor growth significantly in Mdm4Tg15 females, indicating an antagonistic function of estrogen receptors towards Mdm4-mediated cisplatin sensitivity." (PMID 31547268, 2019). "MDMX (MDM4) directly promotes tumor formation and promotes genomic instability." (PMID 31489110, 2019). "We monitored a cohort of 2MX-S:Mdm4+/Δ2 and 8MX-S: Mdm4+/Δ2 mice for tumor development." (PMID 28460439, 2017).
tumor (continued). "Since this study included tumor-based HPV16 status and a homogenous subgroup of SCCOP, it might minimize the selection bias on the associations of MDM4 polymorphisms with tumor HPV16 status of SCCOP." (PMID 29156829, 2017). "Furthermore, studies in transgenic mice show that overexpression of Mdm4 induced spontaneous tumor formation and accelerated tumorigenesis." (PMID 26471763, 2015). "In line with this, MDM4 amplification has been observed in several tumor forms." (PMID 26471763, 2015). "Combination index values at three different ratios of chiMDM2 and chiMDM4 were calculated in cells with high MDM4 expression with values ranging between 0.20 and 0.72, which showed that these dsRDCs promoted synergistic growth inhibition of tumor cells with high MDM4 expression." (PMID 25621298, 2014). "MDM4 expression is elevated or overexpressed in 10–20% of over 800 diverse tumor types." (PMID 22859999, 2012). "The impact of MDM4 on age of tumor onset in germline mutation carriers has not previously been investigated." (PMID 20520810, 2010). "The impact of MDM4 polymorphism on tumor onset in germline mutation carriers has not previously been studied." (PMID 20520810, 2010). "In agreement with the hypothesis of higher oncogenic properties of MDM4-S in comparison to fl-MDM4, analysis of tumor cell lines and samples has evidenced levels of MDM4-S transcript exceeding those of the fl-MDM4, with a certain frequency." (PMID 19721810, 2009). "The recovery of some of the MDM4 variants, as well as of MDM2, in tumor cells and the analysis of their activity suggest that they may possess tumorigenic activity." (PMID 19721810, 2009). "Low-level MDM4 gain, even of a single copy may allow a critical threshold of MDM4 signaling to be reached and be physiologically important for tumor development, but other 1q candidates should also be investigated." (PMID 18489754, 2008). "In other words, future treatments targeting MDM4 might enhance anti-tumor immunity." (PMID 38281029, 2024). "Moreover, MDM4 may possess context-dependent tumor suppressor functions in addition to its well reported oncogenic function." (PMID 34052831, 2021).
tumor (continued). "Treatment of HCC cell lines with XI-011, a pharmaceutical inhibitor of MDM4 transcription, reduced the expression of both the TFs and MDM4 and impaired tumor growth, suggesting that targeting the MDM4 transcription may provide a rationale for future targeted therapy of HCC." (PMID 33429878, 2021). "Furthermore, we examined the expression of MDM4 transcripts in tumor samples." (PMID 34470609, 2021). "Besides, knockdown of MALAT1 inhibited tumor growth in vivo through miR‐185‐5p/MDM4 axis in NSCLC." (PMID 33146951, 2020). "Potential functional polymorphisms in MDM4 may serve as biomarkers for predicting tumor HPV16 status among SCCOP patients, particularly in non-Hispanic white, never-smokers and never-drinkers." (PMID 29156829, 2017). "Indeed, our findings from stratification analysis have demonstrated that modifying effect of combined MDM4 risk genotypes on SCCOP tumor HPV16 positivity was much higher in never-smokers and never-drinkers." (PMID 29156829, 2017). "Finally, inhibitors that simultaneously interfere with the action of Mdm2 and its heterodimerization partner MdmX/Mdm4 were recently published, again showing a broader activity against tumor cells, and may thus warrant combination strategies with Wip1i." (PMID 27183917, 2016). "Finally, an important issue raised by the identification of MDM4 and MDM2 variants is the need to develop accurate detection systems able to distinguish the fl-MDM molecules from their variants in the tumor samples both at the levels of mRNA as well as of protein." (PMID 19721810, 2009). "AH-cfDNA revealed additional somatic copy-number alterations, including amplifications (i.e., MDM4 and ALK) and deletions (i.e., BRCA2), indicating progressive clonal tumor evolution." (PMID 41465072, 2025). "This commentary discusses the emerging dual roles of RPs in ribosome biogenesis and tumor suppression, with a focus on RPL22’s role in the splicing of MDM4." (PMID 40427096, 2025).
tumor (continued). "In this tumor, copy number variation (CNV) analysis showed that MDM4 amplification dominates the malignant clones, which additionally have either EGFR or PDGFRA amplifications, resulting in increased ChrAcc around these genes." (PMID 38724668, 2025). "Patients with MDM2/MDM4 amplification developed TTF <2 months and showed a clearly accelerated rate of tumor growth compared to that before treatment." (PMID 39530091, 2024). "For instance, dual-target inhibitors targeting MDM4/MDMX and XIAP have shown good tumor inhibition potential and avoidance of MDM2 feedback activation in both in vitro and in vivo models." (PMID 39215364, 2024). "MDM4 expression positively correlates with TMB, HRD, MSI, LOH and the score of immune cell, and its effect on tumor immune function varies according to tumor type." (PMID 38281029, 2024). "The models showed characteristic copy number variations (CNV) of disease-related genes (e.g., MDM4, EGFR, CDKN2A, CDK4, and MDM2) that were fairly consistent with the primary tumor." (PMID 37508520, 2023). "MDMX (also called MDM4), a homolog of MDM2, can also bind to and promote RB degradation in an MDM2-dependent manner, thereby promoting tumor growth." (PMID 36230664, 2022). "For example, the splicing type of Ras and CyclinD1 determines the rate of tumor cell proliferation, PKM alternative splicing changes the type of metabolism, and MDM4 and MDM2 protein isoforms regulate tumor sensitivity to therapy." (PMID 35538281, 2022). "A treated tumor and a skin metastasis sample were obtained in the 16th month, and both showed MCL1, TERT, and MDM4 amplifications." (PMID 34680239, 2021). "By using 2D and 3D assays, we showed that MDM4 affects the early steps of the EOC metastatic process, reducing migration and spreading of tumor cells." (PMID 34052831, 2021). "The third method is tumor genomic biomarkers, such as MDM2/MDM4 amplifications and EGFR alterations." (PMID 34733781, 2021). "The GEP and CNA pattern for the EGFR, CDK4, MDM4, and PDGFRA genes was available in 83/83, 68/83, 68/83, and 68/83 GBM tumor samples evaluated, respectively." (PMID 31963499, 2020). "Currently clinical trials are ongoing with the dual Mdm2/Mdm4 stapled peptide (ALRN-6924), which has been reported to be tolerated well in patients as well as demonstrating anti-tumour activity." (PMID 31784573, 2019). "WES of this second tumor recurrence again showed chromosome 10 and CDKN2A deletion but even more interestingly still high ploidy of the EGFR/MDM4 loci (>10 and >6, respectively)." (PMID 28153049, 2017).
tumor (continued). "In every tumor that exhibited EGFR, PDGFRA, NTRK1, MDM2, MDM4, or CDK4 amplification, the increased copy number was contained within, or contained translocations into, a suspect chromothriptic region." (PMID 26328271, 2015). "One particular oncogene which has gained significant interest is MDM4 (Mouse Double Minute 4), a structural homologue of MDM2, thought to promote tumourigenesis via its ability to inhibit the tumour suppressor function of TP533." (PMID 26095524, 2015). "The copy number amplification can also be calculated based on the values of log2 ratio and tumor cellularity, as in specimen HCC01 which had 7-copy amplification of MDM4 and PIK3C2B." (PMID 25469175, 2014). "miR-191 also displayed tumor-type specific roles in tumorigenesis, as miR-191 represses MDM4 and CDK6 expression in ovarian and thyroid follicular cancer, thereby delaying cancer progression and tumor-related death." (PMID 24603541, 2014). "Based on the values of log2 ratios and 57% tumor cellularity, the numbers of copy gains in the amplified regions on 1q of HCC01 were estimated to be four and seven copies (including gains of MDM4 and PIK3C2B), respectively." (PMID 25469175, 2014). "These are necessarily limited in number because of the rarity of the tumor, but nevertheless, a substantial number had MDM2 and/or MDM4 copy-number amplification." (PMID 24321497, 2013). "MDM4 is expressed in breast tissue and is amplified and overexpressed along with LRRN2 and PIK3C2B in breast and other tumor types (TCGA)." (PMID 23544013, 2013). "For the discordant MDM4 SNP7 samples, 4 were heterozygous (T/C) in the germline sequence and homozygous (T/T or C/C) in the tumor sequence." (PMID 22916154, 2012). "The genomic region spanning MDM2 SNP309 and MDM4 SNP7 were PCR amplified and sequenced from both germline and tumor DNA samples." (PMID 22916154, 2012). "Furthermore, eight target genes (COL4A3, FAM30A, FCRL5, MDM4, SYNE2, TNFRSF13C, TPTEP2, VAMP1) were systematically positively correlated with ESR2 expression patterns in tumor types with low ESR2 expression as a prognostic factor concerning OS or DFS." (PMID 39201394, 2024). "The expression levels of MDM4 and MDM2 were higher in the tumor samples than in the normal samples." (PMID 39345743, 2024). "In this work, we did not further explore the different expression genes obtained from transcriptomic sequencing, nor did we delve into the pathways by which MDM4 affects tumor cell immune infiltration." (PMID 38281029, 2024). "Therefore, although it is clear that our results are predominantly dependent on inhibition of MDM4, it is possible that an effect on KIF20A is also contributing to the observed anti-tumor effects." (PMID 33536467, 2021). "It is likely that simple readouts of MDM4 gene and protein expression are not sufficient to predict sensitivity to these drugs that affect a complex cascade of tumor suppressor signaling." (PMID 33536467, 2021).